MTOR (mechanistic target of rapamycin kinase)
Diseases named in the same sentence as MTOR in open-access papers (continued):
Sharing a sentence is not in itself a finding about the gene and the disease.
Hypercholesterolemia (continued). "However, no changes in Akt, p-Akt, mTOR, or p-mTOR were observed following cholesterol lowering gene therapy in sham mice, indicating that isolated mild hypercholesterolemia in control sham mice is not sufficient to induce these alterations." (PMID 31484164, 2019). "However, there is no information whether isolated hypercholesterolemia modulates cardiac autophagy and mTOR pathways in rats." (PMID 28330474, 2017).
kidney (21 papers, 2011 to 2025). "Previous studies suggested that mTOR was activated in most bladder caners and increased p-mTOR status was associated with worsened pathological stage and shortened patient survival." (PMID 24351837, 2013). "Moreover, data from 879 patients treated with several classes of agents as third-line therapies, such as VEGFi and mTOR inhibitors (mTORi), have been reported at recent genitourinary cancers symposium." (PMID 26798533, 2015). "Inflammation and genitourinary cancers are tightly connected, and numerous inflammatory pathways, including the vascular endothelial growth factor (VEGF), von Hippel-Lindau (VHL), the mechanistic target of rapamycin (mTOR), TNF and STAT signaling cascade, are involved." (PMID 36614308, 2023).
lung squamous cell carcinoma (21 papers, 2016 to 2025). "For example, targeting glutaminase with CB-839 (telaglenastat) and mTOR with MLN128 (sapanisertib) overcomes metabolic adaptation to mTOR inhibition in lung squamous cell carcinoma." (PMID 41236698, 2025). "Lung squamous cell carcinoma (LUSC) showed HuR-associated gemcitabine/taxane sensitization (R = 0.38-0.44, p < 0.01) alongside potential mTOR inhibitor (AZD8055) resistance (R = -0.29, p < 0.05)." (PMID 40853971, 2025). "In brief, the results highlight high-YTHDF2 expression predicted a worse prognosis of LUSC, while hypoxia-mediated YTHDF2 overexpression promotes lung squamous cell carcinoma progression by activation of the mTOR/AKT signaling pathway." (PMID 34996459, 2022). "For example, CB-839 can effectively overcome therapy resistance induced by the mTOR inhibitor MLN128 in preclinical animal models of lung squamous cell carcinomas." (PMID 34906193, 2021). "There is currently a phase 1 clincial trial with palbociclib and the PI3K/mTOR inhibitor gedatolisib that is enrolling patients with multiple advanced tumors including squamous cell lung cancer (NCT03065062)." (PMID 30647837, 2018). "Around 74% squamous cell lung cancer samples harbor alterations in RTK/PI3K/AKT/mTOR pathway (RTK 26% and PI3K 47%)." (PMID 29362480, 2018). "In our study, we not only found the overexpression of EIF4G1 in NSCLC besides squamous cell lung carcinoma, but also found that EIF4G1 affects the mTOR signalling pathway in A549 cells." (PMID 33523588, 2021). "Dysregulation of the mTOR pathway is more common in squamous cell lung cancer than in adenocarcinoma, and patients with mutant EGFR always show abnormal PI3K/AKT/mTOR activation, which leads to resistance to clinical treatment with EGFR-tyrosine kinase inhibitor (EGFR-TKI)." (PMID 34195072, 2021).
microcephaly (21 papers, 2017 to 2026). A congenital or acquired developmental disorder in which the circumference of the head is smaller than normal for the person's age and sex. "Instead, mechanistic target of rapamycin (mTOR)-targeted suppression in developing brain caused microcephaly." (PMID 34765564, 2021). "While mutations that inhibit mTOR are associated with microcephaly, hyperactive mTOR signaling is associated with monogenic ASD." (PMID 33642997, 2021). "Knockout of Raptor or mTOR in the developing brain causes microcephaly, reduced neural progenitor proliferation and postnatal lethality, while knockout of Tsc1 or Tsc2 causes macrocephaly and premature neural progenitor differentiation." (PMID 34381067, 2021). "Furthermore, one child in our sample with a de-novo mutation in MTOR, which is a key member in the mTOR pathway that regulates cell growth and proliferation, also exhibited fetal microcephaly (a structural anomaly)." (PMID 39350038, 2024). "In cones, several genes associated with cell migration (LARGE1), mechanistic target of rapamycin (mTOR) signaling (RICTOR), microcephaly (XRCC4), and intellectual developmental disorder (FMN2) were strongly dysregulated." (PMID 40706588, 2025). "It has been reported for animal models that alterations in the mTOR pathway lead to microcephaly during prenatal life as a result of reduced cell number and cell size." (PMID 39350038, 2024). "Akt, a central signaling molecule in the PI3K pathway upstream of mTOR, plays crucial roles in brain development, and non-functional Akt mutation leads to microcephaly." (PMID 34696510, 2021). "Additional phenotypes reported in mice and flies upon GIT1 deletion, such as microcephaly, reduced neuronal size or hyperactivity, might also be related to mTOR modulation." (PMID 34787081, 2021). "Moreover, a recent study on ASD children found an increased risk of microcephaly in mTOR variant carriers as compared to carriers of mutations in non-mTOR genes." (PMID 39350038, 2024). "In addition to a role for ZIKV NS4A in antagonizing RLR signaling, NS4A has been recently discovered to interact with NS4B and induce cellular autophagy in human neural stem cells by interfering with the Akt-mTOR signaling, leading to defective neurogenesis characteristic of microcephaly." (PMID 29988497, 2018). "MTOR is included in MOR3 and deleted in 10 patients, among these 10 patients, 8 presented microcephaly." (PMID 36369750, 2023). "Also, we can hypothesize that MTOR deletion may also be responsible for microcephaly." (PMID 36369750, 2023). "Although the size of RGC apical domains has not been studied, microcephaly and ventricular enlargement have been reported in mouse mutants in which the activity of the mTOR pathway was, respectively, defective or aberrantly elevated." (PMID 27993979, 2017). "Thus, while we cannot rule out a role for dysregulated mTOR signaling in the phenotypes associated with ADSLD, the origin of microcephaly is likely to be mechanistically distinct to that in mTORC1-deficient mouse models." (PMID 35133277, 2022).
myeloid leukemia (21 papers, 2011 to 2026). A clonal proliferation of myeloid cells and their precursors in the bone marrow, peripheral blood, and spleen. "It has been reported that EZH2 inactivation and oncogenic NRAS mutations together activate BCAT1, enhance BCAA metabolism and mTOR signaling, and promote the development of myeloid leukemia." (PMID 39324007, 2024). "Ailanthone and diallyl disulfide, which are the natural compounds from Chinese plants and garlic, respectively, induce autophagy through Beclin1, p62, LC3 expression and mTOR-mediated autophagic death in myeloid leukemia cells." (PMID 36923503, 2023). "In myeloid leukemia cells and macrophages, CaMK4 phosphorylates and inhibits GSK3β, preventing proteasomal degradation of mTOR." (PMID 36002021, 2022). "TQ also inhibits JAK/STAT and PI3K/Akt/mTOR pathways, and consequently inhibits proliferation of myeloid leukemia cells, suggesting that TQ has potential anti-leukemic effects on both AML and CML cells." (PMID 36145344, 2022). "Leucine transport via these transporters is critical for the constitutive activation of the nutrient sensing phosphatidynol-3-kinase (PI3K) and mammalian target of rapamycin (mTOR) pathways in myelogenous leukemias." (PMID 34094976, 2021). "In the present study, we used this experimental approach to show that the natural naphthoquinone shikonin strongly deregulates the IGF1R-Akt-mTOR signaling cascade in U937 myeloid leukemia cells." (PMID 23861714, 2013). "Therefore, genes involved in PI3K/Akt/mTOR signaling provide critical molecular targets for the treatment of myeloid leukemia." (PMID 36145344, 2022). "Thus, conceivably, the marked gain in sensitivity to rapamycin may point to the common activation of Akt/mTOR pathway in myeloid leukemia cells." (PMID 26496029, 2016). "Whereas in myeloid leukaemia, RNF6 promotes tumor growth by activating the PI3K/AKT/mTOR signaling pathway." (PMID 35369571, 2022). "Diallyl disulfide (DADS, a sulfane sulfur donor isolated from garlic) decreased cell viability and increased apoptosis of myeloid leukemia cells (K562 and NB4) by inactivating the mTOR pathway." (PMID 35204649, 2022). "Thus, inhibition of PI3K/Akt/mTOR signaling and re-expression of PTEN protein might provide important therapeutic targets for the treatment of myeloid leukemia." (PMID 36145344, 2022). "The metabolic drug sensitivity profiles generated in a panel of myeloid leukemia cell lines highlight several effective metabolic modifiers such as GSK2194069, AZD3965, and PI3K/mTOR inhibitors that could be clinically explored for a subset of myeloid leukemia patients." (PMID 34907165, 2021).
ovarian clear cell cancer (21 papers, 2012 to 2024). An invasive malignant neoplasm that arises from the ovary and is characterized by a predominance of clear and hobnail malignant epithelial cells. "However, miR-100 was found strongly down-regulated in clear cell ovarian carcinoma and its altered expression was associated with increased expression of mTOR mRNA and protein." (PMID 22920721, 2012). "Because alterations in the PI3K/AKT/mTOR pathway are often found in ovarian clear cell carcinoma, this pathway is one of the promising therapeutic targets." (PMID 35215239, 2022). "Upregulation of PI3K/AKT/mTOR pathway is involved in the tumorigenesis of ovarian clear cell carcinoma, vulvar cancer, and other cancers particularly through mutations and inactivation of PTEN." (PMID 26909602, 2016). "We observed that the presence PIK3CA mutation was associated with high expression of PI3K p110α, p-Akt, mTOR in NSCLC, similar to the results from ovarian clear cell carcinoma." (PMID 24533074, 2014). "The authors also found that the increase of intracellular miR-100 level enhanced therapeutic effect of mTOR inhibitor in clear cell ovarian carcinoma cell line." (PMID 22920721, 2012). "It has been reported that miR-100 is downregulated and targets mTOR in clear cell ovarian cancer and childhood adrenocortical tumors." (PMID 23173671, 2012). "mTOR has also been shown to be a possible therapeutic target in both cisplatin-sensitive and cisplatin-resistant clear cell ovarian carcinoma." (PMID 23237306, 2012). "MiR-100 has been shown to be down-regulated in clear cell ovarian carcinoma cell lines and its over-expression in them inhibited mTOR signaling and enhanced sensitivity to rapamycin analog RAD001 (everolimus) (Table-2)." (PMID 23237306, 2012). "The combination of everolimus (a mTOR inhibitor) and 5-aza-2-deoxycytidine (a demethylating agent) can effectively inhibit the production of ovarian clear-cell cancer stem-like or spheroid cells by inhibiting the COL6A3-AKT-mTOR pathway and exerting an anti-tumor effect." (PMID 39125689, 2024). "In adrenocortical cancer cells and in clear cell ovarian cancer, miR-100 targets mTOR." (PMID 26241472, 2015). "MiR-99 was reported to mediate down-regulation of mTOR/FGFR3 and suppress tumor growth; miR-100 is known to inhibit mTOR signaling and enhance sensitivity to Everolimus in clear cell ovarian cancer; and mTORC1 was recently reported to regulate miR-1 in skeletal myogenesis." (PMID 24009623, 2013). "In a comparison of miRNA expression levels between clear cell ovarian cancer and normal ovarian surface epithelium, the most downregulated miRNA found was miR-100, which targets FRAP1/mTOR and FGFR3, both of which are effectively pro-growth, pro-cancer proteins." (PMID 24152442, 2013). "Certain mutations, such as ARID1A mutations, and alterations in the phosphatidylinositol 3-kinase (PI3K)/AKT/mTOR pathway, which are specific in ovarian clear cell carcinoma (OCCC) and endometrioid ovarian carcinoma (EnOC), may offer additional therapeutic targets in these clinical entities." (PMID 32455595, 2020). "Somatic activating mutations in the PIK3CA gene were found in more than 10% of high-grade serous and 40% of clear cell ovarian carcinomas, and constitutive activation of the PI3K/Akt/mTOR axis is known to confer drug resistance to many types of cancer." (PMID 29930760, 2018). "For ovarian clear cell carcinoma, in which the PI3K/AKT/mTOR pathway and the MDM2 gene are prognostic factors, AKT and MDM2 inhibitors may prove to be promising therapeutic drugs in the future." (PMID 34885229, 2021). "mTOR is a serine/threonine kinase and downstream effector of the AKT signaling pathway, which has also been shown to be a possible therapeutic target in both cisplatin-sensitive and cisplatin-resistant clear cell ovarian carcinoma." (PMID 23978303, 2013).
ovarian clear cell cancer (continued). "Moreover, PI3K activation did not serve as a predictive marker for the sensitivity of ovarian clear cell carcinoma investigated in Japanese patients cohort to PIK3CA/AKT/mTOR inhibitors." (PMID 38391958, 2024).
soft tissue sarcoma (21 papers, 2012 to 2024). A malignant neoplasm arising from muscle tissue, adipose tissue, blood vessels, fibrous tissue, or other supportive tissues excluding the bones. "According to the results of the current clinical studies, targeted therapy has satisfactory effect on soft tissue sarcomas patients, such as the mTOR inhibitor everolimus." (PMID 29212287, 2017). "BKM120 in combination with IGF1R inhibitor AEW541 and mTOR inhibitor rapamycin have been evaluated in pediatric bone and soft tissue sarcomas." (PMID 28662162, 2017). "In recent years, a more in-depth understanding of the molecular pathophysiology in soft tissue sarcomas has led to increasing exploitation of molecule-targeted novel agents including the mechanistic target of rapamycin (mTOR) kinase inhibitors." (PMID 29212287, 2017). "Pazopanib is the only TKI FDA approved for the treatment of soft tissue sarcomas and has been demonstrated to be well tolerated when combined with mTOR inhibition, including sequential addition for the reversal of TKI resistance in a case report." (PMID 27295141, 2016). "In a recent phase II trial in bone and soft tissue sarcomas, inhibition of mTOR with ridaforolimus resulted in better progression-free survival." (PMID 24447333, 2014). "Both mTOR inhibitors and irinotecan have been used as single agents in soft tissue sarcomas with limited efficacy." (PMID 24216984, 2013). "We completed a phase I trial of the combination of the mTOR inhibitor, temsirolimus, and irinotecan in patients with advanced soft tissue sarcoma." (PMID 24216984, 2013). "mTOR inhibitors have modest inhibitory activity against soft tissue sarcoma except in perivascular epithelioid cell tumors and angiomyolipomas." (PMID 24216984, 2013). "Activation of the PI3K/AKT/mTOR pathway is also well-documented for soft tissue sarcomas (STS)." (PMID 33266502, 2020). "Additionally, a phase I study on the treatment of advanced soft tissue sarcoma and a phase II study on the treatment of OS using a combination of Gem plus mTOR inhibitors are underway." (PMID 33114161, 2020). "Everolimus is the first generation of mTOR inhibitors, and it is a serine-threonine protein kinase in the mTOR signal pathway, which is an important potential target for cancer therapy.Some clinical trials have demonstrated the survival benefit of everolimus in soft tissue sarcomas patients." (PMID 29212287, 2017). "Therefore, the juxtaposition of the pan-PI3K inhibitor (BKM120) and the PI3K/mTOR dual inhibitor (BEZ235) may reveal important information about the design of future molecularly targeted therapies for soft-tissue sarcomas." (PMID 22619567, 2012). "Here, we reported the prognostic/predictive value of HMGA1 for trabectedin in advanced soft-tissue sarcoma (STS) and the effect of inhibiting HMGA1 or the mTOR downstream pathway in trabectedin activity." (PMID 38758230, 2024). "Here, we use a mouse model of primary soft-tissue sarcoma for preclinical testing of doxorubicin and inhibitors of the PI3K pathway: BKM120 (PI3K inhibitor) and BEZ235 (a dual PI3K/mTOR inhibitor)." (PMID 22619567, 2012). "In addition, mTOR inhibition by RAPA decreased microvessel sprout formation in human dermal microvascular endothelial cells and microvessel density in mice bearing soft tissue sarcoma cell line xenograft tumors, producing synergistic effects with radiation." (PMID 34993194, 2021). "The screen also showed that the dual mTOR/PI3K inhibitor BEZ-235 sensitized both DasR and PazR which recapitulates the findings of a recent report on the use of this drug to overcome pazopanib resistance in patient-derived soft tissue sarcoma cells." (PMID 28842319, 2018). "In addition, the mammalian target of rapamycin (mTOR) inhibitor ridaforolimus (RIDA) significantly delayed disease progression in patients with advanced soft tissue sarcoma but did not significantly improve overall survival." (PMID 34970483, 2021).
soft tissue sarcoma (continued). "Rapamycin at the concentration of 100 nM, which is significantly higher than the dose needed to inhibit S6K phosphorylation via mTOR, as described in human soft tissue sarcoma cell lines, did not radiosensitize HTB-182 (DMF, 0.95), SK-MES-1 (DMF, 0.88) or MDA-MB-231 cells (DMF, 1.03)." (PMID 27137757, 2016).
cortical dysplasia (20 papers, 2013 to 2025). "In a microarray study of patients with cortical dysplasia, 10 differentially expressed miRNAs were upregulated, and the mTOR signaling pathway was the most significantly associated." (PMID 36824367, 2023). "Individuals with FE due to focal cortical dysplasia occasionally exhibit somatic variants in genes of the mechanistic target of rapamycin (mTOR) pathway." (PMID 38835882, 2022). "We targeted the gene TSC2, which encodes a negative regulator of mTOR; somatic mutations in this gene have been shown to underlie certain focal cortical dysplasias in humans." (PMID 34969984, 2022). "Focal cortical dysplasia is associated with disruptions in the mTOR pathway, while somatic mutations along the neural migration can cause different extents of cortical malformation, with mutations happening earlier in the process, leading to more extensive lesions." (PMID 39311345, 2024). "In this context, mTOR inhibitor, rapamycin has been successfully used to attenuate seizures and cortical dysplasia in animal models featuring enhanced mTOR activity." (PMID 31134199, 2019). "The authors proposed a molecular subregional effect, according to which variants closer to the NPRL2/NPRL3 binding site (where DEPDC5 binds to exert its inhibitory effect on the mTOR pathway) may lead to more severe phenotypes featuring cortical dysplasia." (PMID 36067010, 2023). "As precision treatments for neurogenetic disorders are being investigated, such as mTOR inhibitors for cortical dysplasia, implementing CSF liquid biopsy for aetiological diagnosis will become increasingly important as a surrogate for brain-derived DNA to diagnose brain-specific somatic disorders." (PMID 33738444, 2021). "It makes intuitive sense that disruption of the mTOR (mammalian target of rapamycin) pathway may result in a continuum of changes ranging from cortical dysplasia to megalencephaly, however how many epileptogenic foci are truly caused by mutations?" (PMID 26933590, 2015). "In cortical dysplasia (CD) rodent model brains, we found decreased GLUT1, elevated mammalian target of rapamycin (mTOR) and monocarboxylate transporter 2 (MCT2) expression, and persistent imbalance in glucose-lactate levels upon seizure induction." (PMID 39483922, 2024). "Indeed, in a mouse model of cortical dysplasia, mutants with a deletion of the PTEN gene, a tumor suppressor, overactivate the mTOR signaling cascade." (PMID 24062718, 2013).